AOC4P (amine oxidase copper containing 4, pseudogene )
Synonyms: AOC4; UPAT
Gene: Long non-coding RNA gene on chromosome 17 (42,865,922 to 42,874,246, forward strand). Ensembl gene ENSG00000291070.
Diseases named in the same sentence as AOC4P in open-access papers:
AOC4P is named in the same sentence as 11 diseases in open-access papers, as found by Europe PMC text mining. Sharing a sentence is not in itself a finding about the gene and the disease. The quoted sentences say what the papers report.
gastric cancer (9 papers, 2019 to 2025). A primary or metastatic malignant neoplasm involving the stomach. "Knockdown of AOC4P inhibits gastric cancer cell proliferation, migration, invasion, and promotes apoptosis in vitro, while reducing tumor growth in vivo." (PMID 40556338, 2025). "The research discovered significant increase of plasma lncRNA (TINCR, CCAT2, AOC4P, BANCR, and LINC00857) in gastric cancer cell lines." (PMID 33473276, 2021). "Similarly, lncRNAs, such as H19, TINCR, AOC4P, BANCR, LINC00857, and CCAT2, are detectable in body fluids and can be used to efficiently differentiate gastric cancer patients from healthy controls." (PMID 34885213, 2021). "Evidence has also shown the involvement of AOC4P in colorectal cancer (CRC) and gastric cancer (GC)." (PMID 32334623, 2020).
hepatocellular carcinoma (2 papers, 2020 to 2021). A malignant tumor that arises from hepatocytes. "AOC4P is a lncRNA involved in hepatocellular carcinoma and colorectal cancer and ADHFE1 is a breast cancer oncogene." (PMID 33892787, 2021). "The copper containing 4, pseudogene (AOC4P) is a recently discovered EMT-related lncRNA that was initially reported in hepatocellular carcinoma (HCC)." (PMID 32334623, 2020).
gastric tumors (1 paper, 2025). "AOC4P is overexpressed in gastric tumors and linked to poor survival and lymphovascular invasion." (PMID 40556338, 2025).
tumor (7 papers, 2015 to 2025). "The reduced expression of AOC4P is closely associated with advanced tumor stage and distant metastasis." (PMID 40556338, 2025). "In line with the results of the in vitro assays, an in vivo experiment indicated that silencing AOC4P led to a remarkable increase in the number, weight and distribution of the tumour." (PMID 32334623, 2020). "Then, a tumour EMT RT-PCR array indicated that certain differentially expressed genes were identified after the knockdown of AOC4P expression." (PMID 32334623, 2020). "To further validate the tumor-suppressive function of AOC4P, we performed an in vivo xenograft assay and a tail vein migration assay using nude mice." (PMID 26160837, 2015). "Taken together, our findings suggest that AOC4P lncRNA acts as an HCC tumor suppressor by enhancing vimentin degradation and suppressing the EMT." (PMID 26160837, 2015). "After validation in 108 HCC specimens, we identified a differentially expressed novel tumor suppressive lncRNA termed amine oxidase, copper containing 4, pseudogene (AOC4P)." (PMID 26160837, 2015). "In conclusion, our data show that the lncRNA AOC4P exerts a tumor-suppressive effect on HCC tumor progression." (PMID 26160837, 2015). "In this study, we identified a novel tumor suppressor lncRNA, termed amine oxidase, copper containing 4, pseudogene (AOC4P), via microarray analysis and subsequent validation in HCC tissue specimens." (PMID 26160837, 2015). "In this study, we identified a novel lncRNA, AOC4P, and demonstrated its tumor-suppressive effect on HCC." (PMID 26160837, 2015). "We have also shown that low expression levels of AOC4P are positively related with an advanced tumour stage and lymph node metastasis in EOC, suggesting that AOC4P could serve as an effective target for anti-metastatic strategies in EOC." (PMID 32334623, 2020). "Evidence also supported that AOC4P regulated tumor cell proliferation and invasion in GC." (PMID 32334623, 2020). "The downregulation of AOC4P in HCC suggested its potential function as a tumor suppressor." (PMID 26160837, 2015). "Furthermore, a correlation analysis of AOC4P expression with clinicopathological parameters revealed that the AOC4P expression level was predominantly decreased in late-stage tumor tissues (Kruskal-Wallis test p = 0.0207) and negatively correlated with tumor size (Wilcoxon rank-sum test p = 0.0551)." (PMID 26160837, 2015). "Microarray analyses revealed several differentially expressed lncRNAs; among them, five novel lncRNAs, TINCR, CCAT2, AOC4P, BANCR, and LINC00857, were detected in tumor tissue samples and pre and post-operative plasma." (PMID 37670949, 2023). "In this study, we found that AOC4P downregulated vimentin expression, thereby reducing HCC tumor growth and metastasis." (PMID 26160837, 2015).
malignant tumors (1 paper, 2021). "Several lncRNAs identified in other malignant tumors, such as HOTAIR, CCDC26, and AOC4P, have also been evaluated in GISTs and were shown to be associated with GIST metastasis and sensitivity to imatinib." (PMID 34218261, 2021).
AOC4P also shares sentences with these, for which no sentence is quoted: breast carcinoma (1 paper); colorectal cancer (1); infection (1); liver cancer (1); lymph node metastasis (1); spontaneous abortion (1).